TTR (transthyretin)
Diseases named in the same sentence as TTR in open-access papers (continued):
Sharing a sentence is not in itself a finding about the gene and the disease.
transthyretin amyloidosis (continued). "Transthyretin amyloidosis (ATTR) is a progressive, life-threatening multisystem disease caused by the misfolding of transthyretin (TTR), which is a homotetramer mainly produced in the liver." (PMID 38020120, 2023). "For example, in transthyretin amyloidosis (ATTR) the amyloid (A) fibril is formed by transthyretin (TTR), a tetrameric transport protein mainly synthesized in the liver, in the choroid plexus and by the retinal pigment epithelial cells." (PMID 37901600, 2023). "Hereditary transthyretin amyloidosis (ATTRv) is an ultra-rare genetic disorder characterised by deposits of misfolded transthyretin (TTR) protein in the body’s organs and tissues." (PMID 36698133, 2023). "Transthyretin amyloidosis (ATTR) is a progressive and systemic disease caused by the misfolding and amyloid aggregation of transthyretin (TTR)." (PMID 37762449, 2023). "PTMs of Cys10 cysteine residue play crucial roles in TTR aggregation in hereditary transthyretin amyloidosis diseases." (PMID 36835140, 2023). "Transthyretin amyloidosis (ATTR) is related to abnormalities of transthyretin (TTR), a protein that acts as a transporter of thyroxine and retinol and is produced predominantly in the liver." (PMID 37869146, 2023). "Transthyretin amyloidosis (ATTR Amyloidosis) is a disorder in which a misfolded protein called transthyretin (TTR) gradually accumulates." (PMID 36263082, 2022). "CA is a progressive infiltrative cardiomyopathy in which deposits of amyloid, either immunoglobulin light-chain (AL) or transthyretin amyloidosis (ATTR), accumulate in the myocardium." (PMID 35260184, 2022). "Transthyretin amyloidosis (ATTR) is a progressive and fatal disease caused by transthyretin (TTR) amyloid fibril accumulation in tissues, which disrupts organ function." (PMID 36375122, 2022). "Transthyretin amyloidosis (ATTR) is due to a genetic defect in the transthyretin (TTR) protein, while chronic kidney disease patients on long-term hemodialysis can suffer from B2 amyloidosis, which is due to the accumulation of beta 2 microglobulin." (PMID 36132587, 2022). "Transthyretin amyloidosis (ATTR) is a rare, progressive fatal disease caused by accumulated transthyretin (TTR) amyloid fibrils in tissues." (PMID 36375122, 2022). "Transthyretin amyloidosis (ATTR) encompasses a group of systemic diseases characterized by the extracellular accumulation of insoluble transthyretin (also known as prealbumin) fibrils." (PMID 34746851, 2021). "Transthyretin amyloidosis (ATTRv) is one of the most common forms of systemic and ocular amyloidosis, due to the deposition of transthyretin (TTR), which is a transport protein mainly synthesized in the liver but also in the retinal pigment epithelial cells." (PMID 34206500, 2021). "Transthyretin amyloidosis (ATTR) is characterized by the buildup of amyloid deposits in multiple organs and is typically associated with mutations in the TTR gene." (PMID 33986266, 2021). "Hereditary transthyretin amyloidosis (hATTR; OMIM#105210) is a life-threatening disorder caused by transthyretin (TTR) protein misfolding." (PMID 33203445, 2020). "Recently, it was reported that dysfunction of TTR was bound up with system diseases and the intervention of TTR improved multiple clinical manifestations of hereditary transthyretin amyloidosis." (PMID 31615521, 2019). "Currently, two types of systemic amyloidosis with relevant cardiac involvement have been identified: light-chain (AL) and transthyretin amyloidosis (ATTR)." (PMID 31083399, 2019). "In this context, transthyretin amyloidosis (ATTR) is increasingly garnering recognition as an underdiagnosed cause of diastolic dysfunction." (PMID 31083399, 2019). "Familial transthyretin amyloidosis (ATTR) is a lethal, autosomal-dominant disorder caused by single base-pair mutations in the TTR gene encoding for the 55 kDa transport protein transthyretin secreted by the liver." (PMID 28573431, 2017).
transthyretin amyloidosis (continued). "In in vivo experiments in mice, AsCas12f-HKRA can target the TTR gene for transthyretin amyloidosis, effectively reduce the expression of TTR, and can also knock in EGFP and coagulation factor F9 genes by HDR to achieve gene therapy for hemophilia mouse models." (PMID 39684395, 2024). "Transthyretin amyloidosis can be hereditary (ATTRv) where the gene bears a pathological variation or acquired wild-type TTR (ATTRwt) where none of the pathogenic variations are found." (PMID 39472905, 2024). "In this condition, almost 30 different proteins are able to form deposits, but the most frequent involved are transthyretin and misfolded monoclonal immunoglobulin light chains, which bring two clinical conditions called transthyretin amyloidosis (ATTR) and light-chain amyloidosis (AL)." (PMID 39519069, 2024). "Totally, almost 30 different proteins are able to form deposits, but the most frequently involved are transthyretin and misfolded monoclonal immunoglobulin light chains, which bring to two clinical conditions called transthyretin amyloidosis (ATTR) and light-chain amyloidosis (AL)." (PMID 39519069, 2024). "In a report from 2021, CRISPR/Cas9-mediated in vivo deletion of transthyretin (TTR), which is mutated in progressively fatal transthyretin amyloidosis, led to a striking decrease of circulating transthyretin protein levels in the peripheral blood of treated patients." (PMID 36483551, 2022). "Hereditary transthyretin amyloidosis (ATTRv) is characterized by a buildup of amyloid deposits consisting of amyloid fibrils derived from the accumulation of unstable conformations of the transthyretin (TTR) protein in different tissues." (PMID 35457333, 2022). "In addition, there were reported cases with coexistence of AL amyloidosis and cardiac transthyretin amyloidosis (ATTR CA)." (PMID 35355963, 2022). "A study published in June 2021, introduced a lipid nanoparticle-delivered CRISPR-Cas9 genome editing tool to treat individuals affected by transthyretin amyloidosis (ATTR amyloidosis), a life-threatening disease caused by progressive accumulation of misfolded transthyretin (TTR)." (PMID 34451862, 2021). "Transthyretin Amyloidosis (ATTR) is a severe systemic and fatal disease caused by a misfolding and aggregation of the normal, non-mutated transthyretin protein (wild-type ATTR) or by a heterozygous mutation in the TTR gene (hereditary/variant ATTR) that promotes misfolding and aggregation." (PMID 37788558, 2023). "Established in 2007, the Transthyretin Amyloidosis Outcomes Survey (THAOS) is an ongoing, global, longitudinal, observational survey of patients with ATTR amyloidosis, including both hereditary and wild-type disease, and asymptomatic carriers with TTR mutations." (PMID 37946256, 2023). "Established in 2007, the Transthyretin Amyloidosis Outcomes Survey (THAOS) is the largest ongoing, global, longitudinal, observational study of patients with ATTR amyloidosis, including both hereditary and wild-type disease, and asymptomatic carriers of pathogenic TTR mutations." (PMID 37946256, 2023). "Transthyretin amyloidosis (ATTR) encompasses two distinct pathologies based on whether the amyloid fibrils originate from the intact molecule of TTR: wild-type ATTR (ATTRwt), also known as senile systemic amyloidosis, or from mutations occurring in the TTR gene (ATTRv)." (PMID 38288300, 2023). "Established in 2007, the Transthyretin Amyloidosis Outcomes Survey (THAOS) is the largest ongoing, global, longitudinal observational study of patients with ATTR amyloidosis, including both inherited and wild-type disease, and asymptomatic carriers of pathogenic TTR mutations (NCT00628745)." (PMID 35717381, 2022). "Established in 2007, the Transthyretin Amyloidosis Outcomes Survey (THAOS) is the largest ongoing, global, longitudinal observational study of patients with ATTR amyloidosis, including both inherited and wild-type disease, and asymptomatic carriers of pathogenic TTR mutations." (PMID 35717381, 2022).
transthyretin amyloidosis (continued). "There is a growing portfolio of approved and investigational transthyretin amyloidosis (ATTR) treatments that differ in their mechanisms and effects on circulating TTR." (PMID 40717228, 2025). "Similarly, Inotersen, also a PS gapmer with 2′-MOE-modified ends, targets transthyretin (TTR) mRNA to prevent the production of dysfunctional TTR proteins, which accumulate as deposits causing sensorimotor and autonomic neuropathy in hereditary transthyretin amyloidosis (hATTR)." (PMID 40004514, 2025). "Transthyretin amyloidosis (ATTR amyloidosis) is a progressive and fatal disease characterized by the accumulation of misfolded transthyretin (TTR) protein in tissues." (PMID 38785523, 2024). "The decline in serum TTR portended worse survival in wild-type ATTR-CA patients, which was considered as an independent predictor of OS in patients with transthyretin amyloidosis." (PMID 36776255, 2023). "Transthyretin amyloidosis(ATTR) is a group of fatal diseases describedby the misfolding and amyloid deposition of transthyretin (TTR)." (PMID 36306808, 2022). "Transthyretin amyloidosis (also known as ATTR amyloidosis) is a systemic, life-threatening disease characterized by transthyretin (TTR) fibril deposition in organs and tissue." (PMID 32967612, 2020). "Transthyretin amyloidosis (ATTR) is an autosomal dominant degenerative disease characterized by the formation of amyloid fibril deposits, mainly composed of transthyretin (TTR), in different organs and tissues." (PMID 26147092, 2015). "An early report on the treatment of Transthyretin amyloidosis by LNP encapsulating Cas9 mRNA and transthyretin (TTR)-targeted sgRNA has already entered the third clinical phase, which was the first in vivo CRISPR gene editing therapy approved for advanced clinical development." (PMID 41535643, 2026). "Transthyretin (TTR) is a tetrameric transporter of retinol and thyroxine that aggregates in the central and peripheral nervous system upon a severe pathology known as transthyretin amyloidosis." (PMID 41520423, 2026). "In our study, humanized RBP4/TTR mice (mice with humanized transthyretin and retinol binding protein 4) and RBP4/TTRVal50Met mice (mice with hereditary transthyretin amyloidosis) were established and divided into three groups by different genotypes and treatment strategies." (PMID 40765557, 2025). "Promising current clinical trials for direct in vivo Cas9 gene editing strategies are based on lipid nanoparticle (LNP)-mediated Cas9 delivery for the treatment of hereditary angioedema and for transthyretin amyloidosis, by disrupting liver expression of KLKB1 or TTR, respectively." (PMID 41271724, 2025). "The most common are: light-chain (AL) amyloidosis associated with the presence of multiple myeloma and cardiac transthyretin amyloidosis (ATTR), either wild-type (non-mutated) transthyretin (ATTRwt) or variant transthyretin (ATTRv)." (PMID 38132218, 2023). "However, a recent paper provides another clue, reporting that the TH carrier protein transthyretin (TTR), which is the major T4 carrier in CSF and is expressed mainly in the choroid plexus and leptomeningeal epithelium, seems to be present in Corpora amylacea in hereditary transthyretin amyloidosis." (PMID 36834621, 2023).
AL amyloidosis (153 papers, 2005 to 2026). AL Amyloidosis is a plasma cell disorder characterized by the aggregation and deposition of insoluble amyloid fibrils derived from misfolding of monoclonal immunoglobulin light chains usually produced by a plasma cell tumor. "More than thirty precursor proteins have been identified in humans, but systemic disease in adults is mainly caused by immunoglobulin light chains (AL amyloidosis) or transthyretin (ATTR amyloidosis)." (PMID 41464866, 2025). "Two of these patients had a pathogenic TTR variant (p.Val142Ile) and one had AL amyloidosis with elevated cardiac biomarkers." (PMID 39981348, 2025). "Previous studies demonstrate a remarkable difference in prognosis between AL‐CM and TTR‐CM, especially untreated AL amyloidosis associated with a median survival of approximately 6 months in patients with heart failure." (PMID 39873364, 2025). "The most prevalent types of systemic amyloidoses are associated with the deposition of fibrils composed of transthyretin, either wild type (ATTRwt) or variant (ATTRv) proteins, or monoclonal immunoglobulin light chains (AL amyloidosis)." (PMID 41011213, 2025). "Amyloidotic fibrils originating from misfolded transthyretin and light chains are the causal agents in the most frequent subtypes, i.e., ATTR and AL amyloidosis." (PMID 38202290, 2024). "Al amyloidosis, transthyretin, and echocardiography associated with disease typology, pathological essence, and diagnosis were frequently mentioned." (PMID 36805827, 2023). "It is an infiltrative disease that can be caused by many subtypes of systemic amyloidosis, with greater than 98% being caused by transthyretin (ATTR) or AL amyloidosis." (PMID 37081462, 2023). "The precursors of amyloid fibrils, able of determining a relevant cardiac infiltration, are immunoglobulin-free light chains (AL amyloidosis) and transthyretin (TTR) (both wild and mutated types)." (PMID 35325395, 2022). "Technetium Tc 99m-3,3-Diphosphono-1,2-propanodicarboxylic acid scan was recently suggested to be capable of differentiating TTR-associated amyloidosis from AL amyloidosis." (PMID 20676282, 2009). "CA is caused, in the vast majority of cases, by either TTR or AL amyloidosis." (PMID 33817700, 2021). "An Isoleucine 122 gene mutation of TTR DNA is known to be associated frequently with a milder degree of cardiac involvement compared with AL amyloidosis and is present in 4% of African-Americans, and 23% of African-Americans with cardiac amyloidosis have this variant." (PMID 20676282, 2009). "IHC enables differentiation between amyloid types: κ/λ light chains for AL amyloidosis, transthyretin for ATTR, and serum amyloid A for AA." (PMID 41596468, 2026). "Given the substantial differences in treatment and prognosis between TTR and AL amyloidosis, accurate differentiation between these subtypes is critical for delivering optimal patient care." (PMID 41024906, 2025). "As amyloid fibrils can deposit and disrupt multiple organ systems, most AL amyloidosis patients present with involvement of three or more organ systems and those with TTR often have both cardiomyopathy and neuropathy or combinations of multiple symptoms." (PMID 40114122, 2025). "Among more than thirty different types of amyloid protein involved, those more likely to be associated with cardiac involvement are misfolded immunoglobulin light chain (light-chain amyloidosis—AL) and transthyretin (transthyretin amyloidosis—ATTR)." (PMID 39200875, 2024). "The superficial peroneal sensory nerve showed a slow decrease in SNAP of 35 ± 40% at 24 months follow-up in AL amyloidosis patients compared to TTR patients, where the decrease was even slower, 21 ± 22% for the same period." (PMID 39768907, 2024). "The existence of amyloid structures is particularly intriguing, given that light chain amyloidosis of transthyretin and immunoglobulins leads to amyloid deposition in soft tissues." (PMID 39193017, 2024).
AL amyloidosis (continued). "Nonetheless, the most frequent ones are AL amyloidosis (68%), AA (12%), TTR-related (hereditary 6.6% and acquired 3.2%), and other infrequent subtypes." (PMID 40027091, 2024). "Among the 9 amyloidogenic proteins accumulating in the myocardium to cause significant cardiac disease, the most prevalent are monoclonal immunoglobulin light chain (AL amyloidosis) and transthyretin (ATTR)." (PMID 39139790, 2024). "It involves the misfolding of normally soluble proteins into insoluble amyloid fibrils, with transthyretin and light-chain amyloidosis being the most common forms affecting the heart." (PMID 39092395, 2024). "CA stems most commonly from the immunoglobulin light chain (monoclonal AL or primary amyloidosis) and transthyretin (ATTR)." (PMID 39857663, 2024). "Amyloidotic fibrils originating from misfolded transthyretin and light chains are the causal agents in ATTR and AL amyloidosis." (PMID 38202290, 2024). "More than 98% of CA is due to transthyretin-associated amyloidosis cardiomyopathy (ATTR-CM), in its hereditary (ATTRv-CM) or wild-type form (ATTRwt-CM), or to primary amyloidosis (AL-CM)." (PMID 36983274, 2023). "99mTc-labeled radiotracer cardiac scintigraphy excels at differentiating and confirming the diagnosis of transthyretin CA following adequate screening and ruling out light-chain amyloidosis, obviating the need for more invasive biopsy approaches." (PMID 35414854, 2022). "Differentiation between transthyretin (ATTR) and light chain (AL) amyloidosis is crucial for proper treatment implementation." (PMID 35659266, 2022). "Previous studies report that the H/CL ratio of ≥1.5 on 1 h images or H/CL ratio ≥ 1.3 on late (3 h) images of 99mTc-PYP scintigraphy can clearly distinguish TTR from AL amyloidosis with over 90% sensitivity and specificity." (PMID 36290299, 2022). "Light chain (AL), reactive (AA), mutant or wild type transthyretin (ATTR), fibrinogen (AFib) and apolipoprotein A-I (ApoA1) are the most usual types of systemic amyloidosis, with AL amyloidosis being the most frequently diagnosed in developed world." (PMID 35348907, 2022). "CA presents in two distinct forms: ATTR amyloidosis, which is due to deposition of transthyretin in myocardium, and AL amyloidosis, which is a plasma cell dyscrasia distinct from multiple myeloma." (PMID 34336147, 2021). "Transthyretin (TTR) and the immunoglobulin light chain (AL) are the two major proteins that cause systemic amyloidosis, namely ATTR amyloidosis and AL amyloidosis, respectively." (PMID 34361762, 2021). "Several pilot studies have found PET imaging to be effective as a tool in both diagnosing CA, and useful in differentiating between TTR and AL amyloidosis." (PMID 33195479, 2020). "The most common forms result from the deposition of monoclonal immunoglobulin light chains (AL amyloidosis) or transthyretin, either wild type (wtATTR) or mutant (ATTR) protein." (PMID 26664895, 2015). "AL amyloidosis arises from plasma cell-derived light chains and typically follows an aggressive clinical course, whereas ATTR amyloidosis results from misfolded wild-type or variant transthyretin and progresses more indolently." (PMID 41681748, 2026). "AL amyloidosis results from the deposition of immunoglobulin light chains produced by clonal plasma cells, whereas ATTR amyloidosis is caused by the misfolding of transthyretin protein, which can occur in either its wild-type form (wtATTR) or hereditary-type form (hATTR)." (PMID 40019577, 2025). "Thus, AL amyloidosis should be excluded when ordering a bone scintigraphy scan for diagnosing TTR-CA." (PMID 36290299, 2022). "In addition, 50 patients (51%) had multiple myeloma and 39 (40%) had systemic amyloidosis, 3 of which had the transthyretin type." (PMID 35887884, 2022). "The two most common forms are monoclonal light chain amyloidosis (AL), and transthyretin (TTR) CA." (PMID 31878928, 2019).